ENSG00000252049
Synonyms: LOC124900299
Gene: Small nucleolar RNA gene on chromosome 10 (23,166,985 to 23,167,101, forward strand). Ensembl gene ENSG00000252049.
Gene Ontology:
Biological process: RNA processing
Cellular component: nucleolus
Homologues: Orthologues: mouse Gm26251 (67% identical). Paralogues in human: SNORA40 (74% identical), SNORA40B (74% identical), SNORA40C (69% identical).